CERS2 (ceramide synthase 2)
Diseases named in the same sentence as CERS2 in open-access papers (continued):
Sharing a sentence is not in itself a finding about the gene and the disease.
Arrhythmia (1 paper, 2025). Any cardiac rhythm other than the normal sinus rhythm. "In conclusion, our study indicates that VLC dihydroceramide accumulation in cardiomyocytes is promoted by CerS2 activity and is associated with arrhythmias, atrial fibrillation and heart failure." (PMID 40725105, 2025). "Taken together, these studies indicate that lowering expression of CERS2 would potentially be beneficial by reducing the susceptibility for atrial fibrillation and arrhythmias." (PMID 40725105, 2025). "In conclusion, our findings indicate that increased abundance of VLC-dihydroceramides, promoted by increased activity of CerS2 in response to hypoxia, could play a role in cardiac arrhythmias and heart failure." (PMID 40725105, 2025). "Taken together, our findings indicate that increased abundance of VLC dihydroceramides, promoted by increased activity of CerS2 in response to hypoxia, could play a role in cardiac arrhythmias and heart failure." (PMID 40725105, 2025).
cardiac hypertrophy (1 paper, 2025). "Recently, we reported that with CERS2 KD alone, we observed changes in many pathways crucial for worsening cardiac hypertrophy, suggesting CERS2 KD and the corresponding reduction of cellular levels of VLC sphingolipids, by itself, influence a HF phenotype within these cells." (PMID 41003018, 2025). "We hypothesize that the lipid products generated by CerS2—VLC ceramides—are protective during cardiac hypertrophy, while the products of CerS5/6—LC ceramides—promote the progression and development of hypertrophy." (PMID 41003018, 2025). "The key finding in this study is that CERS2 KD leads to pathway changes that support a more severe HF progression, while CERS5/6 KD leads to less aggressive changes in pathways crucial to cardiac hypertrophy progression." (PMID 41003018, 2025).
cerebellar degeneration (1 paper, 2018). Degeneration of the cerebellum. "In the brain, CerS2 is highly expressed in the myelin-formed oligodendrocytes, and disruption of CerS2 in mice produces myelin disorders such as myelin sheath defects and cerebellar degeneration." (PMID 28842833, 2018).
Cerebral ischemia (1 paper, 2023). Restriction of arterial blood supply to the brain associated with insufficient oxygenation to support the metabolic requirements of the tissue. "The accumulation of ceramides induced by SIRT3 is an important cause of cerebral ischemia–reperfusion injury, which is achieved through the activation of deacetylation of CerS1, CerS2, and CerS6 by SIRT3." (PMID 36374406, 2023). "However, an experiment conducted in 2016 showed that SIRT3 is activated by a currently unknown mechanism and increases the deacetylation level and activity of CerS1, CerS2, and CerS6 after cerebral ischemia–reperfusion." (PMID 36374406, 2023).
cutaneous melanoma (1 paper, 2020). A primary melanoma arising from atypical melanocytes in the skin. "A genome-wide association study has identified the 1q21.3 chromosomal region, containing LASS2 gene that encodes ceramide synthase 2 (CerS2), as a locus predisposing to cutaneous melanoma." (PMID 32858889, 2020).
cystic fibrosis (1 paper, 2021). Autosomal recessive disorder caused by pathogenic variants in the CFTR gene (cystic fibrosis transmembrane conductance regulator), which encodes a chloride and bicarbonate channel expressed in epithelial cells, and follow the diagnosis criteria. "The importance of ceramides containing VLSFA, especially C22:0 and C24:0, for clearance of pulmonary infections has been shown previously in CerS2-deficient mice and in patients with cystic fibrosis, and modulation of this imbalance might be a possible drug target for managing pulmonary infections." (PMID 34684385, 2021).
dermatitis (1 paper, 2019). An inflammatory process affecting the skin. "Although the expression levels of CerS2 and CerS3, which prefer long-chain FAs as a substrate, were mildly elevated in FAg-induced dermatitis, those of CERs with long-chain FAs were decreased." (PMID 30838224, 2019). "In FAg-induced dermatitis, the expression of CerS1, CerS4, and CerS5 decreased, whereas the expression of CerS2 and CerS3 mildly increased with statistical significance." (PMID 30838224, 2019).
endothelial dysfunction (1 paper, 2016). In vascular diseases, endothelial dysfunction is a systemic pathological state of the endothelium (the inner lining of blood vessels) and can be broadly defined as an imbalance between vasodilating and vasoconstricting substances produced by (or acting on) the endothelium. "Endothelial dysfunction, which was manifested in the form of diminished NO bioavailability, was well compensated for by an increased expression of KCa3.1 protein, as shown in aged wild‐type, CerS2 null, and catalase−/−/GPX1−/− mice, and an upregulation of KCa3.1 channel activity." (PMID 27363720, 2016).
Huntington disease (1 paper, 2022). Huntington disease (HD) is a rare neurodegenerative disorder of the central nervous system characterized by unwanted choreatic movements, behavioral and psychiatric disturbances and dementia. "Due to the specificity of CerS2 for C22–C24 fatty acyl chains, Spearman’s correlations were used to determine relationships for both Huntington’s disease and control subjects." (PMID 35169703, 2022). "Post-translational modifications to ceramide synthase 2 may be driving the distinctive sphingolipid profile shifts of the caudate in advanced Huntington’s disease." (PMID 35169703, 2022). "Additional banding of CerS2 was identified in 4 of the 13 Huntington’s disease subjects." (PMID 35169703, 2022). "The possibility of post-translational modifications of CerS2 driving these changes cannot be excluded, as these may contribute to the striatum’s vulnerability to sphingolipid, and possibly mitochondrial dysfunction in Huntington’s disease." (PMID 35169703, 2022). "CerS2 expression (∼40 kDa) was not correlated with age at death or CAG repeat length in Huntington’s disease subjects in either the caudate or putamen." (PMID 35169703, 2022).
Hyperglycemia (1 paper, 2018). An increased concentration of glucose in the blood. "Clozapine caused robust reductions in hepatic ceramide and sphingolipid levels (p < 0.0001), upregulated CerS2 (p < 0.05) and ELOVL1 (+ 37%) and induced significant hyperglycemia (vs controls)." (PMID 29720183, 2018). "Clozapine causes a robust reduction in hepatic ceramide and sphingomyelin levels, coupled with a potentially compensatory upregulation of ceramide synthesising enzymes (CerS2 and ELOVL-1), in the presence of hyperglycemia and evidence of hepatic ER stress." (PMID 29720183, 2018).
Hypertension (1 paper, 2024). The presence of chronic increased pressure in the systemic arterial system. "Considering the effects of RTN3 on autophagy, we further confirmed that increased RTN3 promoted CERS2 selective autophagy and then reduced the levels of ceramide and S1P in HUVECs, which may disrupt endothelial barrier function and ultimately induce hypertension." (PMID 38352050, 2024).
ichthyosis (1 paper, 2025). Disorders of cornification that are characterized by visible scaling and/or hyperkeratosis of most or all of the skin. "Therefore, the loss of ceramides and sulfated cholesterol owing to deficiencies in CerS2, CerS3 and SULT2B1 is implicated in not only the reduction of barrier function but also the pathogenesis of skin diseases such as psoriasis and ichthyosis." (PMID 40637102, 2025).
Impaired glucose tolerance (1 paper, 2019). An abnormal resistance to glucose, i.e., a reduction in the ability to maintain glucose levels in the blood stream within normal limits following oral or intravenous administration of glucose. "While CerS2 knockout animals fed a high fat diet, similar to the western diet, display reductions in the C24 series, upregulation of C16:0-ceramide and subsequent impaired glucose tolerance accompanied by high insulin concentration and loss of insulin sensitivity." (PMID 31067249, 2019).
lipidosis (1 paper, 2018). "Both, SMPD2, which is potentially responsible for lipidosis (a lipid storage disorder in mammals), and CERS2, which encodes a protein associated with cancer growth suppression and involved in sphingolipid synthesis, were increased in expression during the photostimulated M state." (PMID 30538637, 2018).
lysosomal storage disease (1 paper, 2017). A metabolic disorder caused by mutations in proteins critical for lysosomal function, including lysosomal enzymes, lysosomal integral membrane proteins, and proteins involved in the post-translational modification and trafficking of lysosomal proteins. "For example, the increased levels of C16-SLs in CerS2 null thymocytes might affect lysosomal loading of other self-antigens onto CD1d, as occurs in some mouse models of lysosomal storage diseases, where massive accumulation of SLs and GSLs occurs." (PMID 29163475, 2017).
neuroblastoma (1 paper, 2019). Neuroblastoma (NB) is the most common solid, extracranial childhood tumor. "Another reason for the decreased migratory potential in the CERS2-knockdown cells could be explained through another study in neuroblastoma." (PMID 31636736, 2019).
neuropathy (1 paper, 2024). A disorder affecting the nervous system that manifests with pain, tingling, numbness, and/or muscle weakness. "It is conceivable that a subgroup of the patient cohort still exhibits low CerS2 expression after paclitaxel treatment, which is associated with higher SA1P levels and a higher occurrence of neuropathy." (PMID 39347767, 2024).
pheochromocytoma (1 paper, 2019). "A study invested the development of pheochromocytoma in ceramide synthase 2 null mice, and found that ceroid can accumulate rapidly in CerS-2 null mouse adrenal gland, and also mitochondrial become nonfunctional in drenal gland." (PMID 30988071, 2019).
retinal detachment (1 paper, 2020). An eye emergency condition which may lead to blindness if left untreated. "In humans, rhegmatogenous retinal detachment was found to be associated with a missense coding single-nucleotide polymorphism in the Hox domain of CERS2, resulting in an elevated expression level of CERS2." (PMID 32111086, 2020).
Sepsis (1 paper, 2024). Sepsis is defined as life-threatening organ dysfunction caused by a dysregulated host response to infection. "RBP dysfunction disturbs alternative splicing of lipid metabolism genes, such as SREBF1/CerS2, indicating RBPs as possible therapeutic targets for sepsis-induced liver injury." (PMID 38727856, 2024).
squamous cell carcinoma (1 paper, 2019). A carcinoma arising from squamous epithelial cells. "The only squamous cell carcinoma cell line in this study, SCaBER, was the 2nd highest CERS2-expressing cell line." (PMID 31636736, 2019).
type 1 diabetes (1 paper, 2018). "The reduced expression of CERS2 is particularly interesting since this points towards altered hydrocarbon chain lengths of beta cell sphingolipids in type 1 diabetes, with lower amounts of long chains." (PMID 29671030, 2018).
viral infection (1 paper, 2017). "IFNα is critical for defense against virus infection but, unexpectedly, levels of IFNα were higher in CerS2-null liver 2 DPI compared to WT mice and downstream components of IFNAR1 signaling pathway were unaltered." (PMID 29163475, 2017). "Likewise, levels of plasmacytoid dendritic cells (pDCs), the major source of IFNα after viral infection, were increased in CerS2 null liver." (PMID 29163475, 2017). "The redundant role of iNKT cells in splenic viral infection explains why CerS2 null mouse spleen was not more susceptible to LCMV infection." (PMID 29163475, 2017). "The percent of CD4+ T cells was lower in CerS2-null mouse liver before and after viral infection." (PMID 29163475, 2017). "Since the number of CD4+ T cells was decreased in CerS2 null mouse liver, we examined levels of iNKT cells, which form a major fraction of hepatic CD4+ T cells and are involved in protection against pathogens, including viral infection." (PMID 29163475, 2017).
tumor (35 papers, 2013 to 2024). "CERS2 mRNA levels are also found to be low among high-grade meningioma patients who suffer from tumor recurrence more frequently, and have increased risk of death." (PMID 33568634, 2021). "In GBC tissues, elevated expression of SPTLC1 and CERS2, and that of their product C24-ceramide, was associated with tumor stage, distal metastasis, and poor prognosis." (PMID 34439378, 2021). "The loss of CerS-2 expression is related with oncogenic properties through the loss of its role as a tumor suppressor." (PMID 30988071, 2019). "Moreover, a nude mice model showed the combination of CerS-2 overexpression and Dox treatment caused significant decreases in tumor size and weight with respect to controls." (PMID 30988071, 2019). "However, the molecular mechanism underlying CerS-2-mediated inhibition of tumor invasion and metastasis in cancers remains unclear." (PMID 30988071, 2019). "PLA2 plays a role in the inflammatory response, while ceramide synthase CerS2 is involved in sphingolipid metabolism, contributing to the suppression of tumor metastasis." (PMID 39000236, 2024). "Given that LCA, an established tumour promoter, has been implicated in CRC metastasis and is primarily presented within the colon, we examined the expression of Cers1, Cers2, Cers5, and CERK in LCA-stimulated human intestinal epithelial cells." (PMID 37298127, 2023). "CERS2 plays a pivotal role in multiple survival mechanisms, and manipulating its expression and activity can significantly affect cell proliferation and tumor progression." (PMID 37958652, 2023). "In conclusion, different expression data sets and clinical samples show upregulation of the gene in early stages of tumor development, which is consistent with the role found for CERS2 in other malignancies." (PMID 37958652, 2023). "In breast cancer patients, inverse relationships between CerS2 expression and tumor progression, lymph node metastasis, and HER2 expression were discovered." (PMID 37760612, 2023). "A decreased level of CerS2 inhibits tumor growth and metastasis in meningioma, bladder cancer, and PC." (PMID 37760612, 2023). "Several studies have supported the role of CerS2 as a tumor suppressor protein and in maintaining cell- and tissue integrity." (PMID 37760612, 2023). "In human HCC tissue, a low expression of CerS2 correlates with tumor progression and poor prognosis." (PMID 37760612, 2023). "In this regard, it has been proposed that CERS2 promotes the apoptosis of tumor cells through ceramides." (PMID 37958652, 2023). "We also quantified the CERS2 expression using immunohistochemistry, and found a ~1.7-fold increase in CERS2 protein expression in tumor tissues as compared to normal tissues." (PMID 33568634, 2021). "Next, we validated the predicted AS1 event of CERS2 in Luminal B tumor tissues excised from Indian patients to strengthen the pathological significance of this event across race and ethnicity." (PMID 33568634, 2021). "We show that ceramide synthase 2 (CERS2) undergoes a unique AS event where Exon 8 is skipped in Luminal B subtype patients, and validate the differential expression of CERS2 isoforms in Luminal B representative cancer cells and tumor tissues." (PMID 33568634, 2021). "Homo sapiens ceramide synthase 2 (CerS-2) plays an important role in inhibiting invasion and metastasis of tumor cells and has been reported as a tumor metastasis suppressor gene in diverse cancers." (PMID 30988071, 2019). "Remarkably, expression of CerS-2 mRNA was significantly correlated with clinical stage, depth of tumor invasion and recurrence." (PMID 30988071, 2019). "By combining genomic, epigenetic, and expression data to identify clinically significant tumor biomarkers, CerS-2 expression is predicted to be a useful, functionally relevant biomarker." (PMID 30988071, 2019). "Recent studies about diverse cancers have indicated the importance of Homo sapiens ceramide synthase 2 (CerS-2) as a tumor-suppressor gene." (PMID 30988071, 2019).
tumor (continued). "This was because there were a smaller proportion of Stage 4 tumours that displayed moderate expression of CERS2." (PMID 31636736, 2019). "Ceramide synthase 2 (CerS2) is involved in sphingolipid metabolism and suppresses tumor metastasis." (PMID 39000236, 2024). "However, and in spite of the previous studies supporting the idea that lower CERS2 expression is associated with poor prognosis in BC, there are cases in which an increase in CERS2 mRNA expression is observed early in tumor development." (PMID 37958652, 2023). "Therefore, the increase in the expression of CERS2 protein in Luminal B tumor tissue, in all probability, arises from full-length PC and elevated AS1 transcripts." (PMID 33568634, 2021). "In addition to its fundamental function as a very-long-chain ceramide synthase, CERS2 has been shown to inhibit tumor invasion and metastasis." (PMID 33568634, 2021). "The variation in protein size between cancer cell lines and tumor tissues in immunoblot might be due to post-translational modifications as CERS2 protein undergoes glycosylation, and the extent of glycosylation may be different in cell lines and tumor tissue." (PMID 33568634, 2021). "Interestingly, while a greater proportion of Stage 4 tumours expressed high levels of CERS2 as compared to other tumour stages, there was also a comparatively greater percentage of Stage 4 tumours that expressed low levels of CERS2." (PMID 31636736, 2019). "Tumor status induced a significant increase in the expression of CerS2 (p < 0.0001), CerS6 (p < 0.0001), DEGS2 (p < 0.0001), SMPD1 (p < 0.05), and CLN3 (p < 0.0001); and a significant decrease in the expression of UGT8 (p < 0.0001) compared with expression in the corresponding non-tumor tissue." (PMID 26528430, 2015). "Also supporting the tumor suppressor activity of CERS2, an epidemiology study based on SNPs showed that a particular substitution, which favors RNA instability and reduces transcript abundance, acts as an independent risk factor of BC susceptibility and clinical prognosis in the Chinese population." (PMID 37958652, 2023). "The Cers2 gene plays a role in the regulation of cell growth, BCL2 encodes an outer mitochondrial membrane protein that can block apoptosis in cancer cells, PTEN is a tumor suppressor that can be mutated in cancer cells, and MALAT1 is a noncoding RNA that is highly expressed in the nucleus." (PMID 31618108, 2020). "Expression of CERS2 PC and AS1 transcripts were determined by qRT-PCR in tumor and adjoining normal tissue pairs using event-specific primer pairs." (PMID 33568634, 2021). "They found EVs enriched in the polypeptide N-acetylgalactosaminyltransferase 1 (GALNT1) and ceramide synthase 2 (CERS2) mRNAs only in cancer patients, while finding EVs enriched in the tumor suppressors, ARHGEF39, and FOXO3 mRNAs only in controls." (PMID 34445131, 2021). "Altogether, the significant differences in the expression of CerS2, CerS6, DEGS2, SMPD1, and UGT8 sphingolipid genes in tumor tissue go hand in hand with elevation of ceramide levels." (PMID 26528430, 2015). "Nevertheless, no statistical significant differences in CERS2 protein expression across different tumour stages and grades were identified in this study." (PMID 31636736, 2019). "Another experiment showed that CerS-2 is a protective gene against DEN-induced liver carcinogenesis, and deletion of CerS-2 in hepatocytes results in the earlier occurrence of DEN-induced tumors and more rapid tumor growth in vivo." (PMID 30988071, 2019). "There were no obvious distinctions between high- and low-CERS2-expressing cell lines in terms of the grade of the primary tumour, molecular subtype (basal, mixed, and luminal) and genetic stability." (PMID 31636736, 2019). "This analysis of the role of CerS-2 in PCC may lead to further understanding of the mechanism of development of PCC and may implicate the sphingolipid pathway as a possible novel therapeutic target for this rare tumor." (PMID 30988071, 2019).